PPARG (peroxisome proliferator activated receptor gamma)
Diseases named in the same sentence as PPARG in open-access papers (continued):
Sharing a sentence is not in itself a finding about the gene and the disease.
influenza infection (21 papers, 2010 to 2025). "PPARγ has also been implicated in proper tissue repair after influenza infection, as PPARγ-deficient mice exhibited increased collagen deposition in the lungs." (PMID 37701041, 2023). "We treated mice with PPARγ agonist troglitazone prior to influenza infection and evaluated viral burden, weight loss, inflammatory cell differentiation in bronchoalveolar lavage fluid (BALF), and acute lung injury." (PMID 36091002, 2022). "Our results are consistent with the results from Jie Sun’s group that PPARγ deficiency enhaces mouse susceptibility to influenza-induced mortality." (PMID 36091002, 2022). "More research is needed to verify the association of PPARG rs17793951 with humoral response to influenza vaccine and reveal its physiological mechanisms." (PMID 34745208, 2021). "Univariate and multivariate logistic regression analyses were used to explore the association of SNPs in LEP, LEPR, and PPARG with humoral immune response to influenza vaccine." (PMID 34745208, 2021). "The results further suggested that PPARG rs17793951 polymorphism played an important role in immune response to influenza vaccine." (PMID 34745208, 2021). "The present study demonstrated the association between PPARG rs17793951 AG + GG genotype and low responsiveness to influenza vaccine in the Chinese Han population." (PMID 34745208, 2021). "The stratified analysis found the gender difference in the association of LEPR and PPARG variants with immune response to influenza vaccine." (PMID 34745208, 2021). "To investigate the roles of LEP, LEPR, and PPARG in the humoral immune response to influenza vaccine, we conducted an association study to compare the genotypic frequencies of 11 tag SNPs in these genes between the two groups in the Chinese Han population." (PMID 34745208, 2021). "Haplotype TG comprised of PPARG rs796313 and rs17793951 was associated with a 2.85-fold increased risk of low responsiveness to influenza vaccine." (PMID 34745208, 2021). "This study aimed to elucidate the association of SNPs in LEP, LEPR, and PPARG with humoral immune response to influenza vaccine in the Chinese Han population." (PMID 34745208, 2021). "The risk of low responsiveness to influenza vaccine in PPARG rs17793951 AG + GG genotype was almost 3 times higher than that of AA genotype in multivariate logistic regression analysis." (PMID 34745208, 2021). "In terms of repair, one study showed that PPARγ deficient mice had an increase in pulmonary collagen deposition following influenza infection, demonstrating PPARγ’s role is proper tissue repair post-infection." (PMID 35003101, 2021). "Association of SNPs in LEPR and PPARG with influenza vaccine-induced humoral responses stratified by gender." (PMID 34745208, 2021). "In this study, we aimed to investigate the potential association of leptin gene (LEP), leptin receptor gene (LEPR), and peroxisome proliferator activated receptor gamma gene (PPARG) polymorphisms with humoral immune response to influenza vaccine." (PMID 34745208, 2021). "Moreover, PPARG rs17793951 AG + GG genotype was associated with a higher risk of low responsiveness to influenza vaccine in males and females, but this effect was significant only in females." (PMID 34745208, 2021). "Association between haplotypes of PPARG and low responsiveness to influenza vaccine." (PMID 34745208, 2021). "Although there were some different aspects on subjects’ populations and study design between this research and our study, the results both showed that PPARG rs17793951 variants might play an important role in immune response to influenza vaccine." (PMID 34745208, 2021). "Moreover, when haplotypes were constructed with PPARG rs17793951 and rs796313 SNPs, we found a more significant association between TG haplotype with poor responsiveness to influenza vaccine, which was consistent with single SNP analysis." (PMID 34745208, 2021).
influenza infection (continued). "We found that LEPR rs6673591 GA + AA genotype was correlated with low responsiveness to influenza vaccine only in males (OR = 1.96, 95% CI = 1.05–3.67), and PPARG rs17793951 AG + GG genotype was associated with low responsiveness to influenza vaccine in females (OR = 3.28, 95% CI = 1.61–6.67)." (PMID 34745208, 2021). "It has been reported that PPARγ agonist may prove to have a beneficial effect on influenza infection by causing a reduction in inflammatory cytokines." (PMID 33822489, 2021). "Indeed, our study found that PPARG rs17793951 was associated with immune response to influenza vaccine in additive genetic model and dominant genetic model." (PMID 34745208, 2021). "Under physiological conditions, pulmonary PPARγ expression is primarily localized in macrophages, where it supports their proper differentiation and facilitates recovery following influenza infection." (PMID 41385483, 2025). "Our data extend these results to influenza infection in other susceptible species (cotton rats) and show that treatment with the PPARγ agonist PGZ, reverses influenza-dependent inhibition of PPARγ expression." (PMID 36052067, 2022). "In a mouse model of influenza infection, flu virus dose-dependently reduced PPARγ transcriptional activity and decreased expression of PPARγ." (PMID 36091002, 2022). "PPARγ, as well as other transcription factors involved in lipid metabolism (e.g., hepatocyte nuclear factors), are reduced after influenza infection in mice and correlate with the early production of type I IFN." (PMID 36052067, 2022). "Our findings suggest that PPARγ agonists have the potential to be used to limit influenza-related mortality and morbidity." (PMID 36091002, 2022). "This study demonstrates that IAV reduces the transcriptional activity of PPARγ, which is critical for influenza-induced acute lung injury and mortality." (PMID 36091002, 2022). "In conclusion, we performed in vitro and in vivo studies to determine the role of PPARγ in influenza infection." (PMID 36091002, 2022). "Several PPARγ agonists have been documented to attenuate inflammation and alleviate influenza infection in mouse studies." (PMID 36091002, 2022). "The present study identified that influenza infection reduced PPARγ expression and decreased PPARγ transcription activity in human alveolar macrophages (AMs) from different donors." (PMID 36091002, 2022). "One study demonstrated that PPARγ reduced the secretion of influenza-induced proinflammatory cytokines TNF-a, IL-8, and RANTES in humans." (PMID 35003101, 2021). "Considering excessive inflammation is tied to influenza related mortality, PPARγ has been considered as a therapeutic target to limit such harmful inflammation." (PMID 35003101, 2021). "To determine the relationship between PPARγ expression and influenza infection, we infected mice with influenza and measured the mRNA expression of PPARγ and influenza viral burden at days 4, 8, and 12 post-infection by RT-PCR." (PMID 31159430, 2019). "In this study, we found that influenza infection suppressed PPARγ expression on days 4, 8, and 12 post-infection." (PMID 31159430, 2019). "Further, we found that IFNγ suppresses PPARγ expression during influenza and influenza-MRSA super-infection in mice." (PMID 31159430, 2019). "However, influenza infection triggers a type I interferon receptor-dependent downregulation of PPARγ in alveolar macrophages." (PMID 41385483, 2025). "Mice lacking alveolar macrophages or PPARγ in myeloid cells exhibited decreased survival in response to influenza infection, suggesting that PPARγ in alveolar macrophages may protect against influenza-induced disease." (PMID 36052067, 2022). "Our previous study with genome profiling of human AMs in response to influenza infection suggests that influenza may reduce PPARγ gene expression." (PMID 36091002, 2022).
influenza infection (continued). "The present study first examined whether influenza infection impaired PPARγ signaling in vitro in human primary lung cells, including the alveolar epithelial and macrophage cells." (PMID 36091002, 2022). "Moreover, PPARγ agonist troglitazone significantly reduced high doses of influenza infection-induced lung pathology." (PMID 36091002, 2022). "Nevertheless, the association between SNPs in LEP, LEPR, and PPARG and influenza vaccine-induced immune response has not been revealed in the Chinese Han population." (PMID 34745208, 2021). "In dominant genetic model analysis, the PPARG rs17793951 AG + GG genotype was related with lower response to influenza vaccine in both univariate logistic regression analysis (OR = 2.71, 95% CI = 1.56–4.75) and multivariate logistic regression analysis (OR = 2.81, 95% CI = 1.61–4.92)." (PMID 34745208, 2021). "PPARγ activation also leads to decreased mortality in obese mice infected with influenza." (PMID 35003101, 2021). "PPARγ was downregulated in the lung macrophages of db/db mice after influenza infection." (PMID 33467433, 2021). "Finally, influenza studies have established that 15d-PGJ2 treatment protects mice against lethal influenza infection through a PPARγ-dependent mechanism with a marked reduction in viral load and lung inflammation observed." (PMID 32431755, 2020). "We then hypothesized that increasing PPARγ activation will decrease the inflammatory immune response during influenza and influenza-bacterial super-infection." (PMID 31159430, 2019). "The suppression of pro-inflammatory responses induced by PPARγ agonist during influenza infection is not consistent with increased rosiglitazone associated mortality seen in humans." (PMID 31159430, 2019). "However, PPARγ expression is decreased throughout influenza infection progression (day 4 until day 12)." (PMID 31159430, 2019). "The reduction in influenza burden due to the PPARγ agonist treatment might be due to the restriction of viral entry in epithelial cells or could be due to the enhanced antiviral function of natural killer or cytotoxic T cells." (PMID 31159430, 2019). "It is unclear why PPARγ agonist treatment may have different effects in the context of influenza-bacterial super-infections." (PMID 31159430, 2019). "We determined whether boosting PPARγ activity has an anti-inflammatory effect during influenza infection." (PMID 31159430, 2019). "A recent study has demonstrated that three SNPs in PPARG were significantly related to the baseline level of immunomodulator, Vitamin D, and the authors presumed that PPARG and Vitamin D receptors may interact with each other and participate in immune response to influenza vaccine." (PMID 34745208, 2021). "The most significant result was that PPARG rs17793951 AG + GG genotype was associated with low responsiveness to influenza vaccine, and we also observed that LEPR rs6673591 GA + AA genotype was correlated with low responsiveness to influenza vaccine only in males by stratified analysis." (PMID 34745208, 2021). "Thus, treatments with PPARγ agonists may be a potential candidate to treat influenza infection in obese patients." (PMID 33467433, 2021). "In absence or in the presence of low levels of influenza-induced IL-4, treatment with PPARγ agonist, Pioglitazone (PGZ), enhances M2 macrophage polarization and reduces influenza-induced lung disease." (PMID 36052067, 2022). "Despite viral burden not being detectable on day 12, influenza-induced inflammatory cytokines and chemokines are a possible mechanism involved in suppression of PPARγ late during influenza infection." (PMID 31159430, 2019). "However, the role of PPARγ/RXR ligands in the context of influenza infection is not well understood." (PMID 36052067, 2022). "However, the role of PPARγ during influenza infection is not clear." (PMID 31159430, 2019).
cognitive decline (20 papers, 2011 to 2025). "The Pro12Ala polymorphism of PPARG is tied to cognitive decline, particularly among black males, suggesting a situation-dependent connection [PMID: 29116943]." (PMID 40766923, 2025). "Herein, we investigated the precise mechanism underlying SENP1 and PPARγ in cognitive decline after IH insult." (PMID 34035184, 2021). "A recent study demonstrated that the downregulation of PPARγ is associated with the neuroinflammation in hippocampus and cognitive decline in mice." (PMID 34035184, 2021). "Finally, a significant association between the Pro12Ala genotype of PPARG and an increased rate of cognitive decline was observed among older black males." (PMID 33920138, 2021). "However, the underlying molecular mechanisms mediated by PPARγ, counteracting cognitive decline, need to be thoroughly evaluated." (PMID 31614739, 2019). "In addition, related study has been indicated that the mechanism underlying the neuroinflammation in IH impairment and the resultant cognitive decline may be associated with the activation of PPARγ." (PMID 34035184, 2021). "PPARG activation downregulates NF-κB signaling, reducing neuroinflammation, which is a hallmark of both aging and T2DM-associated cognitive decline." (PMID 41282094, 2025). "SENP1 depletion aggravated neuroinflammation and neuronal apoptosis via promoting the SUMOylation of PPARγ, reducing the level of PPARγ, thus exaggerating IH-induced cognitive decline." (PMID 34035184, 2021). "More specifically, PPARγ agonist treatment was shown to improve cognitive decline in Tg2576 APP mice by normalizing dentate granule cell presynaptic function." (PMID 30383537, 2018). "Based on these findings, we hypothesize that SENP1 regulates microglia-mediated inflammatory response toward IH-induced cognitive decline through the de-SUMOylation of PPARγ." (PMID 34035184, 2021). "Also, a large part of this evidence was corroborated in mice models for each of these neurological disorders, and additionally PPARγ activation improved cognitive decline observed in several neurodegenerative diseases." (PMID 25246934, 2014). "In addition, injection of PPARγ agonist rosiglitazone into the brain of Aβ oligomers treated rats prevented the increase of inflammatory cytokines levels, and this is related to improvement in cognitive decline and prevention of microglia activation." (PMID 38421141, 2024). "Moreover, IAAs exhibit preventive effects on dementia and cognitive decline, which may be mediated by the anti-inflammatory processes driven by PPARγ activation." (PMID 31940997, 2020). "In addition, prevention of cognitive decline in an intracerebroventricular infusion model of Aβ1-40 by telmisartan, a partial PPARγ agonist, was abolished when mice were treated with the PPARγ antagonist GW9662, further supporting a role of PPARγ for neuroprotection." (PMID 22654722, 2011). "We cannot exclude the possibility that IH-induced the decrease of PPARγ in hippocampus through other means, such as increasing oxidative stress response, which led to the cognitive decline." (PMID 34035184, 2021).
familial partial lipodystrophy (20 papers, 2006 to 2025). "Finally, we investigated if rare variants in known familial partial lipodystrophy genes PPARG and LMNA were associated with the adiposity traits defined in this study 8,10,69." (PMID 35773277, 2022). "Homozygous pathogenic mutations in the PPARG (3p25.2) or LMNA (1q22) genes cause a form of generalized lipodystrophy, while heterozygous carriers manifest a form of familial partial lipodystrophy (FPLD)." (PMID 37510094, 2023). "The adverse effect of a lack of lower limb/gluteofemoral fat on metabolism is strikingly apparent in patients with familial partial lipodystrophy, particularly types 2 and 3, due to specific mutations in LMNA and PPARG, respectively." (PMID 34875679, 2022). "Regarding Familial Partial Lipodystrophy (FPLD), the main subgroups, FPLD2 to 6, are associated with pathogenic variants in LMNA, PPARG, PLIN1, CIDEC and LIPE respectively, whereas FPLD1 is thought to be of polygenic origin." (PMID 38678257, 2024). "Partial lipodystrophy syndromes are classified into Familial Partial Lipodystrophy (FPLD) including FPLD1 (Köbberling syndrome), FPLD2 (Dunnigan syndrome, due to mutations in the LMNA gene), FPLD3 (PPARG gene), FPLD4 (PLIN1 gene), FPLD5 (CIDEC gene), FPLD6 (LIPE gene) gene mutations." (PMID 41341138, 2025).
Crohn disease (19 papers, 2011 to 2025). A gastrointestinal disorder characterized by chronic inflammation involving all layers of the intestinal wall, noncaseating granulomas affecting the intestinal wall and regional lymph nodes, and transmural fibrosis. "The same is true for PPARγ, as Crohn’s disease-like ileitis is prevented in disease-susceptible SAMP/Fc mice crossbred with disease-resistant mice due to inheritance of functional PPARγ alleles, and certain polymorphisms in the PPARγ gene have been described as prevalent in Crohn’s disease patients." (PMID 33519451, 2020). "MBF-118, a PPARγ agonist, has successfully completed a phase I trial in healthy volunteers, and a phase IIa trial in Crohn’s disease is underway." (PMID 39451206, 2024). "Future studies should determine whether PPARα, PPARγ, AMPK, and mTOR modulate glycolysis in Crohn’s disease in an AhR-independent manner." (PMID 36131123, 2022).
Huntington disease (19 papers, 2008 to 2025). Huntington disease (HD) is a rare neurodegenerative disorder of the central nervous system characterized by unwanted choreatic movements, behavioral and psychiatric disturbances and dementia. "Furthermore, PPARγ exerts a neuroprotective effect on neurodegenerative disorders including Huntington disease, which is caused by disassociation of mutant Huntingtin protein with REST in the cytoplasm and therefore enhanced nuclear translocation and aberrant accumulation of REST in nucleus." (PMID 23614038, 2013). "This activity at PPARγ has been confirmed in a model of Huntington’s disease where THCA showed neuroprotective activity through a PPARγ-dependent pathway." (PMID 33498245, 2021). "VCE-003.2 showed neuroprotective effects in a murine model of Huntington’s disease that was prevented by co-administration of the PPARγ antagonist T0070907 and in a murine model of Parkinson’s disease." (PMID 33498245, 2021). "THCA improved neuronal viability in an animal model of Huntington disease (HD), and decreased striatal neurodegeneration (blocked by PPARγ antagonist), and it was suggested as a therapeutic agent in HD." (PMID 30405366, 2018). "A similar finding was observed in regards to the neuroprotective effects of Rosi on Huntington’s disease which showed that PPARγ, but not PPARα, plays an important role on rescuing motor dysfunction." (PMID 25799429, 2015).